Y_RNA (Y RNA )
Gene: Miscellaneous RNA gene on chromosome 11 (118,970,498 to 118,970,595, forward strand). Ensembl gene ENSG00000222529.
Homologues: Orthologues: chimpanzee Y_RNA (100% identical), guinea pig Y_RNA (76% identical). Paralogues in human: RNY4 (85% identical), RNY4P6 (85% identical), RNY4P9 (84% identical), Y_RNA (84% identical), RNY4P14 (83% identical), RNY4P19 (83% identical), RNY4P3 (83% identical), RNY4P7 (83% identical), Y_RNA (83% identical), RNY4P17 (82% identical), Y_RNA (82% identical), RNY4P10 (81% identical), and 89 more.